GJA1 (gap junction protein alpha 1)
Diseases named in the same sentence as GJA1 in open-access papers (continued):
Sharing a sentence is not in itself a finding about the gene and the disease.
gastric cancer (26 papers, 2013 to 2025). A primary or metastatic malignant neoplasm involving the stomach. "Some studies have shown that the expression level of GJA1 protein is low in gastric cancer tissue, and its low expression is associated with the progression and poor prognosis of gastric cancer, which is consistent with our analysis results but inconsistent with the results of the TCGA database." (PMID 39132501, 2024). "Notably, GJA1 (encoding Cx43) is featured in the list of 20 genes most significantly associated with an unfavourable prognosis in stomach cancer." (PMID 30814684, 2019). "Currently, the specific mechanism of GJA1 in gastric cancer still requires further investigation to provide new ideas and methods for the diagnosis and treatment of gastric cancer." (PMID 39132501, 2024). "To further explore the role of GJA1 in SLC52A3‐mediated malignant phenotype, we co‐transfected GJA1 in SLC52A3‐expressing MGC803 and AGS gastric cancer cells and detected GJA1 expression level by Western blotting." (PMID 32888389, 2020). "This suggests that the role of the GJA1 gene in the occurrence and development of gastric cancer may be complex." (PMID 39132501, 2024). "The function of the GJA1 gene in gastric cancer is still unclear." (PMID 39132501, 2024). "RGS2, GJA1, GPX3, and LOX were less expressed in gastric cancer tissues than in paracancerous tissues (P<0.05)." (PMID 39132501, 2024).
Sepsis (26 papers, 2017 to 2025). Sepsis is defined as life-threatening organ dysfunction caused by a dysregulated host response to infection. "MiR-206 targeted regulating the expression of connexin 43 (GJA1), thereby improving sepsis lung injury by reducing W/D ratio and BALF protein content." (PMID 35279164, 2022).
Alzheimer disease (25 papers, 2014 to 2026). A progressive, neurodegenerative disease characterized by loss of function and death of nerve cells in several areas of the brain leading to loss of cognitive function such as memory and language. "Despite the lack of information about GJA1 in leprosy, this has been described in neural impairment, like in the pathogenesis of Alzheimer's disease, where GJA1 downregulation leads to reduced levels of ApoE." (PMID 35492305, 2022). "YAP1 and GJA1 act as related hub genes in Alzheimer’s disease." (PMID 37744228, 2023). "GJA1 has been previously investigated in the context of Alzheimer’s disease." (PMID 30577786, 2018). "Besides, GJA1 knockout could provide neuroprotective effect in Aβ induced astrocytes, which indicated that GJA1 might improve Alzheimer's disease." (PMID 35279164, 2022).
Obesity (24 papers, 2015 to 2025). Accumulation of substantial excess body fat. "Gja1 ablation in mesenchymal lineage cells protects against obesity-induced BAT whitening and increases cold-induced thermogenesis and lipolysis in mice fed an HFD." (PMID 38349739, 2024). "In the current study, we validated the depot-specific gene expression of GJA1, DES, DSP, and SMOC2 in intra-individually paired SAT and OVAT samples from 78 individuals with obesity from our in-house cohort using quantitative PCR." (PMID 41275133, 2025). "Gja1 ablation in adipocytes does not protect against diet-induced obesity and actually worsens glucose tolerance." (PMID 38349739, 2024).
dilated cardiomyopathy (22 papers, 2011 to 2026). Cardiomyopathy which is characterized by dilation and contractile dysfunction of the left and right ventricles. "Our previous study also found that miR-1 was involved in VMC via post-transcriptional repression of GJA1, and miR-21 regulated the progression of VMC to dilated cardiomyopathy (DCM)." (PMID 27213338, 2016). "Furthermore, in another model of dilated cardiomyopathy, CELF1 was found to regulate GJA1 mRNA degradation through an interaction with the nuclear-specific exoribonuclease RRP6, leading to Cx43 downregulation." (PMID 37791351, 2023).
cervical carcinoma (21 papers, 2013 to 2025). A carcinoma arising from either the exocervical squamous epithelium or the endocervical glandular epithelium. "We evaluated the role of GJA1 in cervical cancer (CC) using public data from The Cancer Genome Atlas (TCGA) and the Gene Expression Omnibus (GEO) database." (PMID 33299882, 2020). "GJA-1 was recently characterized as a key gene for cervical cancer invasion and metastasis and is down 120-fold in NuKO cells." (PMID 27144453, 2016). "GJA1 was shown to be positively correlated with the poor overall survival of cervical cancer." (PMID 35371339, 2022). "To address the concern that a GFP tag may interfere with cellular localization of GJA1 isoforms, we took advantage of the previously characterized cervical carcinoma cell line, C33A, that expresses endogenous GJA1-20k." (PMID 29163229, 2017). "Additionally, numerous studies have indicated that GJA1 could be a promising prognostic marker for poor survival and a therapeutic target in cervical cancer, suggesting a key regulatory role across various cancers." (PMID 39777350, 2024).
colon carcinoma (21 papers, 2011 to 2024). "Importantly, GJA1/Cx43 has been reported to be frequently mutated in tumors of the colon, suggesting that inactivation of Cx43 can be involved in colorectal carcinogenesis." (PMID 21754925, 2011). "Similarly, PPARβ/δ also regulates novel metastasis genes such as GJA1, VIM, SPARC, STC1, and SNCG, accelerating the aggressiveness of colon cancer cells." (PMID 37251321, 2023).
infarction (21 papers, 2009 to 2025). A localised pathological necrosis of tissue resulting from obstruction of the blood supply usually by a thrombus, an embolus, or vascular torsion. "We have also observed that increase in miR-206 expression reflected an increase in cerebral infarct volume while correlating to the downregulation of the Gja1 mRNA." (PMID 23823624, 2013).
glaucoma (19 papers, 2010 to 2026). Increased pressure in the eyeball due to obstruction of the outflow of aqueous humor. "Presently, TDRD7, CYP1B1, GJA1, IL1B, MMP1, and MMP3 have been considered as a causative gene for glaucoma." (PMID 33299458, 2020). "For example, Aqp4, astrotactin 1 (Astn1), contactin 1 (Cntn1), and gap junction protein alpha 1 (Gja1) were down-regulated after optic nerve crush, but were up-regulated in glaucoma." (PMID 23826199, 2013). "In human patients with glaucoma, GJA1 expression is higher than in age-matched healthy volunteers." (PMID 36769067, 2023). "Connexin 43 encoded by the Gja1 gene also has pivotal roles in maintaining the ocular microenvironment, and a recent study has suggested that GJA1 gene variation is associated with an elevated risk for glaucoma because astrocytic connexin is essential for gap junction formation." (PMID 36769067, 2023).
pancreatic cancer (19 papers, 2012 to 2025). "For example, in pancreatic cancer, exosomal miR-30b-5p promotes tumor angiogenesis by inhibiting GJA1, while miR-27a promotes angiogenesis by targeting BTG2." (PMID 39596828, 2024). "Meanwhile, the hsa-miR-30d-5p/GJA1 axis is a likely pathway involved in pancreatic cancer metastasis." (PMID 36741258, 2023). "CTNNA1, CTNNB1, and CTNND1 are key molecules potentially involved in pancreatic cancer metastasis mediated by hsa-miR-30d-5p/GJA1." (PMID 36741258, 2023). "We found that hypoxic pancreatic cancer derived exosomes promoted angiogenesis through miR-30b-5p/GJA1 axis." (PMID 35173549, 2022). "Our study demonstrated that hypoxic pancreatic cancer cells promoted angiogenesis through transferring exosomal miR-30b-5p to endothelial cells to regulate directly the expression of GJA1." (PMID 35173549, 2022). "Here, our study found that hypoxic pancreatic cancer derived exosomal miR-30b-5p regulated the expression of GJA1 in endothelial cells to promote angiogenesis." (PMID 35173549, 2022). "No study is available that characterized the functional significance of HELLPAR in cancer progression although a previous study proposed a potential role of HELLPAR as a ceRNA of miR‐30d‐5p and a regulator of the miR‐30d‐GJA1 signaling axis in pancreatic cancer." (PMID 35612714, 2022). "Taken together, these results suggest that pancreatic cancer cells in hypoxic tumor microenvironment secret large amounts of exosomes, which encapsulate mature miR-30b-5p and transfer them to endothelial cells to suppress the expression of GJA1, and promote tumor angiogenesis." (PMID 35173549, 2022).
astrocytoma (18 papers, 2014 to 2024). "Connexin-43 [Cx43 or gap junction A1 (GJA1)] has been identified as the gap junction protein involved in tumor microtubes (TM) communication in astrocytomas, facilitating tumor progression, network communication and resilience to adverse events." (PMID 39026284, 2024).
ovarian carcinoma (17 papers, 2010 to 2025). A malignant neoplasm originating from the surface ovarian epithelium. "For example, TGF-β upregulated GJA1 expression in human granulosa cells and ovarian cancer cells but downregulated GJA1 expression in rat HSCs." (PMID 34693020, 2021).
Hyperglycemia (15 papers, 2011 to 2025). An increased concentration of glucose in the blood. "Decreased GJA1 expression particularly in hyperglycemia accelerates apoptosis." (PMID 21689475, 2011).
hearing loss (12 papers, 2011 to 2026). "Mutations in Gja1 (Cx43), Gjb2 (Cx26), Gjb3 (Cx31), and Gjb6 (Cx30), which constitute gap junctions, can cause non-syndromic hearing loss." (PMID 34199197, 2021). "Mutations in connexin genes—Cx26 (GJB2), Cx30 (GJB6), Cx29 (GJC3), Cx31 (GJB3) and Cx43 (GJA1)—have been identified as the culprits for hearing loss with distinct pathological changes in the cochlea." (PMID 33917368, 2021). "Although defects in GJB4 and GJA1 in humans are known to cause hearing loss, GJB4 can be expressed in immature cardiomyocytes." (PMID 33048975, 2020). "Cx30 (GJB6), Cx29 (GJC3), Cx31 (GJB3), and Cx43 (GJA1) mutations can also cause hearing loss with distinct pathological changes in the cochlea." (PMID 26074771, 2015). "Furthermore, mutations in GJA1, encoding Cx43, can also contribute to hearing loss." (PMID 37373495, 2023).
renal fibrosis (12 papers, 2013 to 2025). A final common manifestation of a wide variety of chronic kidney diseases characterized by glomerulosclerosis and tubulointerstitial fibrosis. "TSN reduced renal fibrosis and improved pathological damage in the kidney in vivo through the regulation of GJA1, CTGF, MMP7, and CCL5, which are genes associated with ECM deposition." (PMID 34539795, 2021). "GJA1 prevents the proliferation of renal fibrosis in DN by improving oxidative stress as well as downregulating TGF-β1 levels." (PMID 34539795, 2021). "Furthermore, it was verified that TSN could regulate the levels of GJA1, CTGF, MMP7, and CCL5 and alleviate renal fibrosis in DN." (PMID 34539795, 2021).
brain tumor (11 papers, 2016 to 2025). "On the molecular level, all three cell cycle arrest genes that were upregulated under combination therapy in our study (GADD45A, CDKN1A, and BTG2), where Cx43 function was inhibited, showed a positive correlation with GJA1 levels in brain tumor tissue." (PMID 39680504, 2025). "The biological context of an intrinsic low level of GJA1 in untreated brain tumor tissue may differ significantly from a therapy‐induced reduction in GJA1." (PMID 39680504, 2025).
ischemic cardiomyopathy (11 papers, 2017 to 2025). Ischemic cardiomyopathy is a cardiomyopathy in which a weakness in the muscle of the heart due to inadequate oxygen delivery to the myocardium with coronary artery disease being the most common cause. "Indeed, it has been proposed that GJA5 can be increased to compensate for the loss of GJA1 in ischemic cardiomyopathy and DCM." (PMID 33048975, 2020).
non-small cell lung carcinoma (11 papers, 2008 to 2025). A group of at least three distinct histological types of lung cancer, including non-small cell squamous cell carcinoma, adenocarcinoma, and large cell carcinoma. "In contrast, Cx43 expression was found to be lower in non-small cell lung cancers compared to adjacent normal tissues, owing to promoter methylation, which prevents GJA1 gene activation." (PMID 39766090, 2024).
viral infection (11 papers, 2017 to 2026). "Conversely, viral infection did not alter the expression of genes encoding adhesion molecules, such as GJA1 and ITGB1, unlike what was observed upon infection at higher MOI (0.5)." (PMID 37569398, 2023). "Since knockdown of Gja1 (which expresses the Cx43 protein) impacted LACV infection in vitro, we hypothesized that activating or upregulating Cx43 might reduce virus infection and pathogenesis." (PMID 37202395, 2023).
deafness (10 papers, 2014 to 2024). An inherited or acquired condition characterized by the complete loss of the ability to hear from one or both ears. "Mutation in GJA1 is shown to be associated with non-syndromic autosomal recessive deafness in human." (PMID 34568429, 2021). "Furthermore, GJC3 (encoding Cx30.2/31.3), GJB3 (encoding Cx31), GJB1 (encoding Cx32), and GJA1 (encoding Cx43) gene mutations have been reported to cause non-syndromic deafness." (PMID 35457072, 2022). "In addition to causing deafness and heart diseases, GJA1 gene mutations mainly result in ODDD." (PMID 35457072, 2022). "In fact, digenic inheritance of nonsyndromic deafness caused by mutations in the GJB2 gene and other connexin genes, such as GJB3, GJB6, GJB4, or GJA1, have been previously reported in several deaf patients." (PMID 25388789, 2014). "Cx43 (GJA1) mutations were also initially linked to non-syndromic autosomal recessive deafness." (PMID 26074771, 2015). "Subsequently, 75 Cameroonian patients with non-syndromic deafness were analyzed through direct Sanger sequencing of the entirety of the coding regions of GJB6 gene and GJA1 pseudo-gene; the large-scale GJB6-D3S1830 deletion was also investigated." (PMID 32098311, 2020).
metastatic tumors (10 papers, 2008 to 2025). "Secondly, although GJA1 has suppressive effects on cancer, many articles have reported the overexpression of GJA1 in metastatic tumors." (PMID 33299882, 2020).
cataract (9 papers, 2015 to 2025). Partial or complete opacity of the crystalline lens of one or both eyes that decreases visual acuity and eventually results in blindness. "HMX1, GJA1, and PROSER3 were identified to be the leading genes associated with cataracts in our older population." (PMID 36009466, 2022). "GJA3 and GJA8, but not GJA1, have been associated with cataracts in previous studies." (PMID 36009466, 2022). "However, the evidence for the involvement of the GJA1 gene in cataracts remains unclear." (PMID 36009466, 2022).
lymphedema (9 papers, 2017 to 2025). Excess fluid collection in tissues, causing swelling. "There also appeared to be fewer VVs in the single patient identified with lymphedema caused by a mutation in GJA1 (CX43)." (PMID 28724617, 2017). "A second case of lymphedema in an ODDD patient related to a GJA1 mutation was reported in 2018." (PMID 34072103, 2021). "Indeed, mutations in the GJC2 and GJA1 genes, encoding for Cx47 and Cx43, respectively, have been linked to primary and secondary lymphedema in various families and populations, which is of major importance for the stratification of lymphedema patients." (PMID 34072103, 2021). "Variants in CX43, encoded by GJA1, and CX47, encoded by GJC2, cause lymphedema in humans, which can be a clinical manifestation of CCLA." (PMID 38618951, 2024). "Genes associated with lymphangiogenesis and the junctional paracellular permeability of vessels such as GJA1, CLDN5 and VEGFR3 were found upregulated only in secondary lymphedema, where true edema is present." (PMID 37108757, 2023).
metastatic melanoma (8 papers, 2011 to 2020). A melanoma that has spread from its primary site to another anatomic site. "Importantly, a strong positive correlation between the expression of HIF1A and GJA1 (encoding for HIF-1α and Cx43, respectively) was observed in a large cohort of metastatic melanoma patients (n = 368), described in The Cancer Genome Atlas (TCGA) database." (PMID 33066331, 2020). "Interestingly, our data also suggest that this phenomenon could occur in patients, given the positive correlation of HIF1A and GJA1 expressions observed in metastatic melanoma TCGA dataset." (PMID 33066331, 2020).
amyloid (7 papers, 2018 to 2025). "Additional astrocyte hub genes in the ETC, including NRXN1, CADM1, MACF1, MAGI2, LRP4, GJA1 and ADGRL3, have been identified as markers of a reactive astrocyte state, implicating them in amyloidosis, regulation of neuroinflammation, cellular interactions." (PMID 38913039, 2024).
Infertility (7 papers, 2019 to 2022). "Homozygous knockout of Gja1, another BTB gene that codes the gap junction protein connexin 43, leads to infertility in mice." (PMID 35813649, 2022).
neuropathy (7 papers, 2017 to 2026). A disorder affecting the nervous system that manifests with pain, tingling, numbness, and/or muscle weakness. "Dead M. leprae increased the expression of WNK, IFNB, IKBKA, and HLA-DQA1 (genes related to neuropathy), in addition to GJA1 and RAF1 (for Schwann cell reprogramming) and KCNJ10, OLIG1, SHH, and SOSTDC1 (for neural regeneration)." (PMID 35492305, 2022).
schizophrenia (7 papers, 2020 to 2026). A major psychotic disorder characterized by abnormalities in the perception or expression of reality. "ROC analysis showed that five genes—MALAT1, PPIL3, ITM2A, MTA2, and GJA1—effectively distinguished schizophrenia from controls (AUC >0.70)." (PMID 41199749, 2025). "Correlation analysis linked OXPHOS scores positively with PPIL3 and ITM2A, negatively with MALAT1 and GJA1, and not significantly with MTA2, suggesting their role in schizophrenia-related mitochondrial dysfunction." (PMID 41199749, 2025).
cognitive decline (6 papers, 2014 to 2024). "Overlapping the proteins consistent in both AD datasets with data from transgenic mice revealed four novel, high-confidence candidates that were associated with cognitive decline and drug-mediated multi-target kinase inhibition: PACSIN1, GJA1, VSNL1 and NDUFB5." (PMID 33530349, 2021).
endometrial cancer (6 papers, 2013 to 2025). Primary or metastatic malignant neoplasm involving the endometrium (mucous membrane that lines the endometrial cavity). "It was shown that GJA1 helps maintain cell differentiation and prevent transformation in endometrial carcinoma." (PMID 34211976, 2021).
erythrokeratodermia variabilis (6 papers, 2019 to 2023). A rare genetic chronic skin disorder characterized by hyperkeratosis and transient erythema. "Mutations to GJB3, GJB4, and GJA1 are linked to erythrokeratodermia variabilis et progressiva (EKVP), a disease characterized by hyperkeratotic plaques and erythematous patches." (PMID 36861039, 2023). "However, Cx43 pathologies can occasionally affect the skin as a set of patients have been identified that harbor GJA1 mutations and present with erythrokeratodermia variabilis et progressiva (EKVP)." (PMID 33066499, 2020).